OR9G4 (olfactory receptor family 9 subfamily G member 4)
Description:
Odorant receptor.
Synonyms: OR11-216
Gene: Protein-coding gene on chromosome 11 (56,741,223 to 56,748,697, reverse strand). Ensembl gene ENSG00000172457.
Subcellular location: Cell membrane
Genetic constraint (gnomAD): Loss-of-function variants: 19 observed, 17.45 expected, observed/expected ratio (o/e) 1.09, 90% interval 0.76 to 1.59. The upper end of that interval is the gene's LOEUF score, 1.59, which puts it in group 6 of 6, group 1 being the genes least tolerant of losing a copy. Missense variants: 428 observed, 391.14 expected, observed/expected ratio (o/e) 1.09, 90% interval 1.01 to 1.18. Synonymous variants: 182 observed, 154.03 expected, observed/expected ratio (o/e) 1.18, 90% interval 1.05 to 1.34.
Homologues: Orthologues: chimpanzee OR9G4 (98% identical), macaque OR9G4 (96% identical), dog OR9G4 (90% identical), mouse Or9g4 (87% identical), rat Or9g4 (87% identical), rabbit OR9G4 (87% identical). Paralogues in human: OR5B21 (54% identical), OR5M10 (53% identical), OR5A2 (52% identical), OR5B12 (52% identical), OR5I1 (52% identical), OR5M1 (52% identical), OR5AR1 (52% identical), OR9I1 (51% identical), OR5A1 (51% identical), OR5AP2 (51% identical), OR8B3 (51% identical), OR5AU1 (50% identical), and 84 more.